DBX2 (developing brain homeobox 2)
Synonyms: FLJ16139
Tractability: No criterion of Open Targets' tractability assessment is met for any kind of drug.
Gene: Protein-coding gene on chromosome 12 (45,014,672 to 45,051,099, reverse strand). Ensembl gene ENSG00000185610.
Subcellular location: Nucleus
Subcellular location (Human Protein Atlas): Nuclear membrane; Nucleoplasm; Vesicles
Gene Ontology:
Molecular function: protein binding; DNA-binding transcription factor activity, RNA polymerase II-specific; DNA binding
Biological process: regulation of transcription by RNA polymerase II; regulation of DNA-templated transcription
Cellular component: chromatin; nucleus
Genetic constraint (gnomAD): Loss-of-function variants: 16 observed, 14.97 expected, observed/expected ratio (o/e) 1.07, 90% interval 0.72 to 1.61. The synonymous counts are far from expectation, so gnomAD's model fits this gene poorly and the ratio says little. Missense variants: 536 observed, 384.7 expected, observed/expected ratio (o/e) 1.39, 90% interval 1.3 to 1.5. Synonymous variants: 254 observed, 165.82 expected, observed/expected ratio (o/e) 1.53, 90% interval 1.38 to 1.7.
Homologues: Orthologues: chimpanzee DBX2 (99% identical), macaque DBX2 (96% identical), pig DBX2 (88% identical), dog DBX2 (87% identical), rat Dbx2 (71% identical), mouse Dbx2 (71% identical), guinea pig DBX2 (52% identical), tropical clawed frog dbx2 (39% identical). Paralogues in human: DBX1 (33% identical), HLX (28% identical), LEUTX (11% identical).
Diseases named in the same sentence as DBX2 in open-access papers:
DBX2 is named in the same sentence as 6 diseases in open-access papers, as found by Europe PMC text mining. Sharing a sentence is not in itself a finding about the gene and the disease. The quoted sentences say what the papers report.
autism spectrum disorder (1 paper, 2022). A spectrum of developmental disorders that includes autism, and Asperger syndrome. "For example, Slc1a2, Prdm16, Kank1 and Ddah1 were target genes of Dbx2, the high expression of Slc1a2 was found to reduce the risk for PD in a Chinese cohort and the other genes are associated with cognitive function, autism spectrum disorder and depression-like behavior, respectively." (PMID 36142685, 2022).
glioma (1 paper, 2016). A benign or malignant brain and spinal cord tumor that arises from glial cells (astrocytes, oligodendrocytes, ependymal cells). "This latter cohort included several genes relevant to progenitor development and migration, including Arx, Dbx2, the semaphorin receptor plexin B3, and the cytoskeletal adaptor Stmn3, which has recently been linked to glioma motility." (PMID 27213272, 2016).
hepatocellular carcinoma (1 paper, 2022). A malignant tumor that arises from hepatocytes. "Cluster 3 was enriched for LHX8 and FEV as well as DBX2, which is differentially expressed in hepatocellular carcinoma." (PMID 36404344, 2022).
infection (1 paper, 2020). The state of being infected such as from the introduction of a foreign agent such as serum, vaccine, antigenic substance or organism. "Surprisingly, despite the widespread infection with the virus, changes in the transcriptome remained limited to only a few genes: GALR3, EGR1, E2F2, RNY4, DBX2 were found upregulated, and ITM2C was downregulated." (PMID 33490061, 2020).
DBX2 also shares sentences with these, for which no sentence is quoted: developmental delay (1 paper); tumours (1).